H2AJ (H2A.J histone)
Description:
Core component of nucleosome. Nucleosomes wrap and compact DNA into chromatin, limiting DNA accessibility to the cellular machineries which require DNA as a template. Histones thereby play a central role in transcription regulation, DNA repair, DNA replication and chromosomal stability. DNA accessibility is regulated via a complex set of post-translational modifications of histones, also called histone code, and nucleosome remodeling.
Synonyms: H2AFJ; FLJ10903; MGC921
Tractability: PROTAC: UniProt records ubiquitination sites on it; ubiquitination databases record sites on it.
Gene: Protein-coding gene on chromosome 12 (14,774,405 to 14,778,002, forward strand). Ensembl gene ENSG00000246705.
Subcellular location: Nucleus; Chromosome
Subcellular location (Human Protein Atlas): Nucleoplasm
Pathways (Reactome):
Gene expression (Transcription): B-WICH complex positively regulates rRNA expression; DNA methylation; ERCC6 (CSB) and EHMT2 (G9a) positively regulate rRNA expression; MLL4 and MLL3 complexes regulate expression of PPARG target genes in adipogenesis and hepatic steatosis; NoRC negatively regulates rRNA expression; PRC2 methylates histones and DNA; RNA Polymerase I Promoter Escape; RNA Polymerase I Promoter Opening; RUNX1 regulates genes involved in megakaryocyte differentiation and platelet function; RUNX1 regulates transcription of genes involved in differentiation of HSCs; Regulation of endogenous retroelements by KRAB-ZFP proteins; Regulation of endogenous retroelements by Piwi-interacting RNAs (piRNAs); Regulation of endogenous retroelements by the Human Silencing Hub (HUSH) complex; SIRT1 negatively regulates rRNA expression; Transcriptional regulation by small RNAs
Chromatin organization: CHD1 and CHD2 subfamily; CHD6, CHD7, CHD8, CHD9 subfamily; ChAHP complex assembly; Interaction of NuRD complexes with transcription factors; NuRD complex assembly; RMTs methylate histone arginines
Cell Cycle: Condensation of Prophase Chromosomes; Deposition of new CENPA-containing nucleosomes at the centromere; Inhibition of DNA recombination at telomere; Packaging Of Telomere Ends
DNA Repair: Cleavage of the damaged purine; Cleavage of the damaged pyrimidine; Recognition and association of DNA glycosylase with site containing an affected purine; Recognition and association of DNA glycosylase with site containing an affected pyrimidine
Signal Transduction: Activated PKN1 stimulates transcription of AR (androgen receptor) regulated genes KLK2 and KLK3; Estrogen-dependent gene expression; Formation of the beta-catenin:TCF transactivating complex; Pre-NOTCH Transcription and Translation
Cellular responses to stimuli: DNA Damage/Telomere Stress Induced Senescence; Oxidative Stress Induced Senescence; Senescence-Associated Secretory Phenotype (SASP)
Developmental Biology: Activation of anterior HOX genes in hindbrain development during early embryogenesis; Chromatin modifications during the maternal to zygotic transition (MZT); Transcriptional regulation of granulopoiesis
Reproduction: Meiotic recombination
and 5 more pathways
Gene Ontology:
Molecular function: structural constituent of chromatin; DNA binding; protein heterodimerization activity
Biological process: heterochromatin formation
Cellular component: extracellular exosome; nucleosome; chromosome; nucleus
Genetic constraint (gnomAD): Loss-of-function variants: 3 observed, 8.76 expected, observed/expected ratio (o/e) 0.34, 90% interval 0.16 to 0.88. That is too few expected variants to judge how well the gene tolerates losing a copy. Missense variants: 128 observed, 186.66 expected, observed/expected ratio (o/e) 0.69, 90% interval 0.59 to 0.79. Synonymous variants: 98 observed, 92.68 expected, observed/expected ratio (o/e) 1.06, 90% interval 0.9 to 1.25.
Homologues: Orthologues: chimpanzee H2AJ (100% identical), pig H2AJ (100% identical), dog H2AJ (99% identical), guinea pig H2AJ (99% identical), macaque H2AJ (99% identical), rabbit H2AJ (99% identical), mouse H2aj (98% identical), rat H2aj (98% identical), zebrafish h2af1al (72% identical), Caenorhabditis elegans htas-1 (52% identical). Paralogues in human: H2AC20 (97% identical), H2AC11 (95% identical), H2AC13 (95% identical), H2AC14 (95% identical), H2AC15 (95% identical), H2AC16 (95% identical), H2AC17 (95% identical), H2AC18 (95% identical), H2AC19 (95% identical), H2AC6 (95% identical), H2AC12 (95% identical), H2AC21 (95% identical), and 15 more.
Diseases named in the same sentence as H2AJ in open-access papers:
H2AJ is named in the same sentence as 15 diseases in open-access papers, as found by Europe PMC text mining. Sharing a sentence is not in itself a finding about the gene and the disease. The quoted sentences say what the papers report.
cancer (7 papers, 2017 to 2025). A tumor composed of atypical neoplastic, often pleomorphic cells that invade other tissues. "Focusing on cancer, elevated H2AJ expression has been detected in several carcinoma types, especially in luminal breast and PCa, which indicates that H2AJ may act as a potential biomarker for identifying these cancer subtypes." (PMID 40075640, 2025).
H2AJ also shares sentences with these, for which no sentence is quoted: tumor (8 papers); breast carcinoma (4); colorectal cancer (2); glioma (2); melanoma (2); prostate carcinoma (2); brain tumors (1); gastric cancer (1); glioblastoma multiforme (1); hepatocellular carcinoma (1); liver fibrosis (1); lymphoma (1); neuroblastoma (1); uterine cancer (1).